MMP2 (matrix metallopeptidase 2)
Diseases named in the same sentence as MMP2 in open-access papers (continued):
Sharing a sentence is not in itself a finding about the gene and the disease.
breast cancer (continued). "For instance, CD147 could promote breast cancer cell metastasis and invasion by contribution of MMP2, MMP9, and VEGF expression, and CD147-mediated chemotaxis of CD4+CD161+ T cells may contribute to local inflammation in rheumatoid arthritis." (PMID 33015178, 2020). "The molecule exerts its principal activity as structural protein, although it is also known to induce and interact with the tissue inhibitor of metalloproteinase-3 TIMP-3, which inhibits metalloproteinases MMP2/9, highly expressed in breast cancers and actively involved in matrix remodelling." (PMID 32972039, 2020). "In addition, association between gallic acid and ECGC attenuated MDR in doxorubicin-resistant breast cancer cells through a concentration-dependent inhibition of metalloproteinases (MMP-2 and MMP-9)." (PMID 31936346, 2020). "In addition, ARG inhibited the metastasis of human breast cancer cells by reducing the activity of MMP2, MMP9, and heparanase protein." (PMID 33015162, 2020). "In conclusion, it is unclear whether HIIT influences levels of MMP in breast cancer patients undergoing anthracycline-based chemotherapy yet MMP-2 was significantly increased both the HIIT and CON group; with no changes on MMP-1, -7, -10, TIMP-1 and -2." (PMID 32246106, 2020). "Additionally, HCT and PR extracts also decreased the migration and invasion of both breast cancer cell lines through inhibition of MMP-2 and MMP-9 secretion." (PMID 32155880, 2020). "In addition, both extracts also inhibited the migration and invasion of breast cancer cells via MMP-2 and -9 abolishment." (PMID 32155880, 2020). "While we hypothesized that HIIT would reduce MMP-2 levels in breast cancer patients undergoing anthracycline-based chemotherapy, MMP-2 levels were significantly increased in both the HIIT and CON groups." (PMID 32246106, 2020). "For instance, in breast cancer cells, piperine inhibited MMP-2 and MMP-9." (PMID 33256185, 2020). "Furthermore, we analyzed if treatment with an MMP2 inhibitor (BB-94, Batimastat) reduces breast cancer invasiveness." (PMID 33087801, 2020). "In addition, MMP2 is also known to serve as an important downstream effector of PI3K/Akt signaling in breast cancer." (PMID 33375117, 2020). "MMP2 and MMP9 expression is known to be highly upregulated in almost every metastatic cancer cell type, and elevated MMP9 level is associated with the high potential of metastasis in several human carcinomas, including breast cancer." (PMID 32708426, 2020). "Although in our study we did not found a significant correlation of rs243865 in MMP-2 with breast cancer risk, the TT genotype found to be less frequent among cases than in controls (4, 3% vs. 8.4%), what is consistent with the previous findings." (PMID 32765800, 2020). "The gelatin in combination with the ADA offers the possibility for cell adhesion through integrin binding and makes matrix remodeling easier for mammalian cells, e.g., through MMP-2, which is often overexpressed in nodular melanoma and breast cancer with less favorable prognosis." (PMID 32824576, 2020). "A meta-analysis, that did not discriminate stromal and tumoral cells, found that high MMP-2 expression was associated with advanced stage, tumor invasion and metastasis in endometrial cancer, and MMP-2 was also shown to correlate with shortened survival in patients with breast carcinoma." (PMID 32669083, 2020). "MMPs, especially MMP9 and MMP2, are crucial biomarkers for migration and invasion in breast cancer." (PMID 31488193, 2019). "Targeting MTA2 with a short hairpin RNA could reduce cell proliferation and inhibit metastasis by downregulating MMP-2 or MMP-9 expression in breast cancer and glioma cells." (PMID 31771219, 2019). "Importantly, serum samples from breast cancer patients have shown that high levels of MMP-2 and MMP-9 are directly associated with metastasis, and further provide evidence of the participation of these MMPs in breast cancer progression." (PMID 31671408, 2019).
breast cancer (continued). "Whereas, upregulation of RBMS3 could alleviate Twist1-induced MMP2 expression and abrogate migration, metastasis ability of breast cancer cells, correspondingly." (PMID 30819235, 2019). "The same investigators later described 10 μM Met-F-AEA to reduce the expression of β-catenin protein and its accumulation in the nuclei of breast cancer cells via CB1 receptor activation associated with downregulation of c-Myc, matrix metalloproteinase-2 (MMP-2) and cyclin D1." (PMID 31143113, 2019). "Besides, TES inhibits the invasion and angiogenesis of breast cancer partially through miR-29b-mediated MMP-2 inhibition." (PMID 30728082, 2019). "However, it has been shown that OPN activates the phosphatidylinositol 3-kinases/Protein kinase B/nuclear factor kappa B (PI3K/AKT/NFKB) pathway inducing uPA secretion and MMP-2 activation in breast cancer cells." (PMID 31475105, 2019). "We also provided a novel mechanism of the RBMS3/Twsit1/MMP2 axis in the regulation of breast cancer invasion and metastasis, which may become a potential molecular marker for breast cancer treatment." (PMID 30819235, 2019). "In summary, our study revealed a novel mechanism of the RBMS3/Twsit1/MMP2 axis in the regulation of invasion and metastasis of breast cancer, which may become a potential molecular marker for breast cancer treatment." (PMID 30819235, 2019). "We focused on the clinical relevance of ENO1 and MMPs (MMP-2 and MMP-9) overexpression in breast cancer tissues: The association between the higher ENO1, MMP-2 and MMP-9 expression with a worse prognosis suggest that the elevated ENO1 and MMPs expression are promising biomarkers for breast cancer." (PMID 31416219, 2019). "In a murine surgical breast cancer model, the anti-metastatic effects of lidocaine under sevoflurane anaesthesia are abolished by the Src inhibitor bosutinib, and lidocaine reduces serum MMP-2." (PMID 31546727, 2019). "Here, we found that ectopic expression of Twist1 could induce MMP2 expression and promote breast cancer migration, invasion and lung metastasis." (PMID 30819235, 2019). "In addition, increased levels of HSP70B (HSP70) contribute to breast cancer metastasis through upregulation of mesenchymal markers such as N-cadherin, MMP2, SNAIL, and vimentin." (PMID 31878360, 2019). "Furthermore, quercetin also induced Akt-mTOR mediated autophagy in breast cancer cells where it reduced the migration and metastasis of cells through MMP-2, MMP-9, and VEGF inhibition." (PMID 31064104, 2019). "However, SRC-3 is a polyomavirus enhancer activator 3 (PEA3) coactivator and in breast cancer cells SRC-3 forms complexes with PEA3 on MMP-2 promoters to enhance its expression." (PMID 31316078, 2019). "Furthermore, as MMP2 is the direct downstream target of Twist1, repression of Twist1 resulted in downregulation of MMP2 expression, thereby inhibiting the metastasis of breast cancer cells." (PMID 30819235, 2019). "Furthermore, we show that downregulation of RITA is associated with reduced MMP2 in trophoblastic HTR and SGHPL-4 cells, and breast cancer cell line MDA-MB-231." (PMID 31766533, 2019). "For example, MMP-2 processing growth factors, including heparin-binding EGF-like growth factor (HB-EGF), in response to gonadotrophin-releasing hormone (GnRH) activation can promote cell proliferation, with HB-EGF activity linked to breast cancer growth." (PMID 29874869, 2018). "MMP-2, in turn, is responsible for generating collagen IV peptides as a byproduct of proteolytic activity—fragments with chemo-attractive properties for bone-marrow-derived cells and future metastatic breast cancer cells recruited to the pre-metastatic niche." (PMID 29874869, 2018). "Similarly, 7-chloro-fascaplysin inhibited cell survival through interference with the PI3K/Akt/mTOR pathway, which in turn modulates HIF-1α, eNOS and MMP-2/9 in a breast cancer cell line." (PMID 30322180, 2018).
breast cancer (continued). "Given the prominent role for MMP-2 activity in breast cancer progression and metastasis, the question remains as to whether the therapeutic targeting this individual MMP family member is feasible." (PMID 29874869, 2018). "In addition, lactate dehydrogenase, which catalyzes the conversion of lactate to pyruvic acid, is essential for the expression of FAK, VEGF, and MMP2 in MDA-MB-231 breast cancer cell line." (PMID 30404206, 2018). "MMP-2 secretion from other host cellular sources can also promote breast cancer growth." (PMID 29874869, 2018). "Here, as a case in point, we focus specifically on MMP-2 as an example to show how it can contribute to each stage of breast-cancer-to-bone metastasis and also discuss novel approaches for the selective targeting of MMP-2 in the setting of the bone-cancer microenvironment." (PMID 29874869, 2018). "Thus, to study the mechanisms of the inhibitive effect of nobiletin on migration of breast cancer cells, we measured the expression of MMP-2 and MMP-9." (PMID 30574046, 2018). "Our results suggest that one of the mechanisms by which TFPI-2 inhibits breast cancer cell invasion could be via the regulation of MMP-2 gene transcription." (PMID 29051606, 2017). "In this work we have compared Fibulin-2 digestion pattern generated by MMP-2 with that produced by ADAMTS-5 activity concluding that Fibulin-2 might be a substrate for both metalloproteases in breast cancer." (PMID 28099917, 2017). "Our results revealed a biological activity of TFPI-2 in the nucleus, which suggests that one of the mechanisms that TFPI-2 suppresses migration and invasion of breast cancer cells could be mediated by the regulation of MMP-2 expression." (PMID 29051606, 2017). "For example, MMP‐2 overexpression is required for breast cancer and brain metastasis." (PMID 28846829, 2017). "Further we conclude that the main contributors to extracellular proteolysis of murine breast cancer TICs are metalloproteases, such as Mmp14, Mmp2, and Mmp13 along with aspartic proteases, because treatment with TAPI-O and Pepstatin strongly reduced DQ-collagen cleavage." (PMID 27542270, 2016). "Cell motility is a critical process of invasion allowing primary tumors to metastasize, and invasion is principally stimulated by the gelatinase matrix-metalloproteinases (MMPs), and especially MMP-2 and MMP-9 were found to elevate in breast cancer and associated with disease progression." (PMID 27363023, 2016). "Among secreted MMPs, the gelatinases MMP-2 and MMP-9 are of particular interest as they can hydrolyze major ECM components, such as gelatin and type IV collagen, and were repeatedly associated with breast cancer progression." (PMID 26883198, 2016). "MMP-2 has been associated with the metastasis of many cancers, including colorectal cancer, ovarian cancer, and breast cancer, but it does not have a clear association with bladder cancer invasion." (PMID 25402510, 2015). "A separate clinical study of fifty breast cancer patients and 34 healthy controls showed higher levels of gelatinase-A (MMP-2) and gelatinase-B (MMP-9) in sentinel lymph nodes containing macroscopic metastatic nodules with respect to lymph nodes that were free of cancer cells." (PMID 25950608, 2015). "Furthermore, the cells expressing MMP-2 are also important and indicative of the aggressiveness of the breast cancer." (PMID 26286584, 2015). "HIF-2α also appears to regulate MMP-2 levels in breast cancer." (PMID 26305551, 2015). "Our experiments with the MMP inhibitors Marimastat and SB-3CT showed for the first time that inhibition of MMP activities can reduce the expression of active integrin β1, suggesting an association between active MMP-2/MMP-9 and integrin β1 protein expression in metastatic breast cancer cells." (PMID 28721370, 2015). "Stromal MMP-2 expression may play a crucial role in predicting aggressive clinical behavior in breast cancer patients." (PMID 26674531, 2015).
breast cancer (continued). "For example, MMP-2 overexpression is required for breast cancer brain metastasis development." (PMID 25402510, 2015). "Besides, it had been demonstrated that Fra-1 directly induced MMP-1 and MMP-9 promoter activities in breast cancer cells and stimulated MMP-2 and MMP-9 expression to enhance the motility and invasion of lung cancer cells." (PMID 26337460, 2015). "MMP-2 in stromal fibroblasts might indicate poor survivors in patients with high grade breast cancer." (PMID 26674531, 2015). "Matrix metalloproteinase 2 (MMP-2) plays a crucial role in the progression of breast cancer (BC)." (PMID 25816052, 2015). "Over-expression of miR-106b-5p was also demonstrated in breast cancer, and the miR-106b/MMP2/ERK pathway might play a pivotal role in bone metastasis of breast cancer." (PMID 25714014, 2015). "Moreover, we showed that elevated STAT3 signaling-mediated upregulation of MMP-2/9 is responsible for the enhanced invasive properties in SK-BR-3/EPR breast cancer cells." (PMID 26501276, 2015). "Increased MMP2 expression was shown to predict adverse outcomes in patients with breast cancers." (PMID 25954957, 2015). "Moreover, previous studies have identified that β-catenin, a transcription factor, involves in breast cancer metastasis via induction of MMP2, MMP-9, and UPA genes." (PMID 25658913, 2015). "Interestingly, OPG and MMP-2 expression were significantly positively correlated in several breast cancer mRNA expression data sets in the public domain, further supporting a functional role for this signaling axis in breast cancer." (PMID 24976340, 2014). "Increased levels of MMP-2 and MMP-9 have been previously associated with lung and breast cancers." (PMID 25025278, 2014). "Because the expression of MMP-2 and MMP-9 has been implicated in the development and progression of many tumors, such as prostate, colorectal, breast cancer and cervical cancer, MMP2 has been deemed to be the most direct and important enzyme in invasion of cancer cells." (PMID 24885858, 2014). "We assessed the activity of one of these proteases, MMP2, by gelatin zymography in the conditioned media of these breast cancer cells treated with azurin and could observe a decrease in its activity." (PMID 23894398, 2013). "IL-19 induces IL-1β, IL-6, TGF-β, and MMP-2 in breast cancer cells." (PMID 23710200, 2013). "We performed immunoblotting studies to investigate whether a decrease in MMP-2 could be correlated with the efficacy of combined effect of sorafenib and radiation in breast cancer." (PMID 23314174, 2013). "Moreover, some reports recently suggested that expression of MMP14 downstream target such as MMP2 correlates with cancer progression in colon and breast cancers 11–40." (PMID 24156018, 2013). "Thus, apart from its anti-VEGF effect in inhibiting tumor cells, this combination treatment can inhibit the metastasis and spread of breast cancer cells by reducing MMP-2." (PMID 23731702, 2013). "In addition, Smad3 has been shown to be an important contributor to breast cancer cell invasion by controlling the expression of MMP-2 and MMP-9, two metalloproteinases involved in matrix degradation and invadopodia functions." (PMID 23405166, 2013). "Interestingly, not only tumor cells themselves produce MMPs, but they are able to induce the expression of proteases in brain endothelial cells, e.g., MMP-2 was shown to be induced in brain endothelial cells after coculture with breast cancer cells." (PMID 23344048, 2013). "Blocking MMP-2 secretion and activation during breast carcinoma development may decrease metastasis." (PMID 23457587, 2013). "Therefore, we next tested the impact of host MMP-2 ablation on this process in an immunocompetent model of mammary tumor induced osteolysis." (PMID 22238668, 2012). "Our studies have focused on MMP-2 in breast cancer cells, but extracellular Hsp90α may be important for other cancers as well." (PMID 21533148, 2011).
breast cancer (continued). "We next investigated whether the endogenous Hsp90α and co-chaperones present in the extracellular media of breast cancer cells can activate MMP-2." (PMID 21533148, 2011). "Thus, our findings implicate a second chaperone, Hsp70, in MMP-2 activation and breast cancer cell migration and invasion." (PMID 21533148, 2011). "Based on its intracellular function, we hypothesized that extracellular Hsp90α enhances breast cancer migration and invasion by activating MMP-2 with the assistance of the co-chaperones, Hsp70, Hop, Hsp40, and p23." (PMID 21533148, 2011). "Moreover, Massagué and coworkers have recently identified MMP2 as one of the genes of the signature that mediates breast cancer metastasis to the lungs, the targeted metastatic organ in our animal model." (PMID 20649976, 2010). "According to previous studies, the p38 MAPK is a central kinase in a common pathway that plays an important role in breast cancer invasion and metastasis by modulating the expression and activity of molecules involved in the degradation of extracellular matrix (that is, MMP-2 and MMP-9)." (PMID 21167057, 2010). "To investigate whether melatonin regulates breast cancer cell invasion by altering the expression of MMPs, particularly MMP-2 and MMP-9, we examined the effect of melatonin on MMP-2 and MMP-9 protein expression in the conditioned medium using MCF-7/6 cells." (PMID 21167057, 2010). "Transfection of CD147 cDNA into human MDA-MB436 breast cancer cells resulted in an enhancement of tumor growth and an increase in metastatic incidences, both of which were directly correlated with high levels of tumor-derived MMP-2 and MMP-9." (PMID 20525232, 2010). "The previously discovered role of claudin-3 and claudin-4 in cell motility and increased MMP-2 activity suggests that this may be yet another metastasis-promoting molecule in breast carcinoma effusions." (PMID 19680458, 2010). "In addition, the expression of MMP-2, -8, -9, -10, -11 and -13 mRNA in breast cancer tissue was identified by RT-PCR." (PMID 19531263, 2009). "This inhibitory effect of ATRA on MMP-2 activity in human breast cancer cells (MCF-7) may result due to its inhibitory effect on MT1-MMP, EMMPRIN, and upregulation of TIMP-2." (PMID 19636436, 2009). "Further, over-expression of TIMP2 in tumour stroma was associated with increased disease-free survival in prostate cancer, and down-regulation of MMP2 by TIMP2 over-expression reduced tumour growth and metastatic potential in a rat model of breast cancer-associated brain metastasis." (PMID 20041153, 2009). "In addition, BER significantly suppresses cell migration and invasion, as well as decreases pro-MMP-9/pro-MMP-2 activation in breast cancer cells." (PMID 19796390, 2009). "Additionally, KP1019 clearly reduces the release of metalloproteases of the extracellular matrix (MMP-2 and MMP-9), enzymes often associated with unfavourable prognosis in many cancers including mammary tumours." (PMID 19789639, 2009). "Indeed, estrogens have been shown to increase levels of active MMP-2 in various tissues and cell types, including breast cancers, and estrogen antagonists reversed that effect." (PMID 18706093, 2008). "Furthermore, selective antagonists for MMP-2/MMP-9 or MMP-3 also suppressed the stimulatory effect of IL-17 on breast cancer invasion, although to a lesser extent than GM6001." (PMID 19014637, 2008). "A zymography gel was performed to determine whether irradiation of Matrigel (reconstituted basement membrane) can increase the secretion of MMP-2 from breast cancer cells." (PMID 17987037, 2007). "Similarly, abundant MMP-11 and MMP-2 immunoreactivity in tissue from patients with breast cancer corresponded to a shorter disease-free survival and poorer overall survival." (PMID 17311017, 2007).